GPX4 (glutathione peroxidase 4)
Diseases named in the same sentence as GPX4 in open-access papers (continued):
Sharing a sentence is not in itself a finding about the gene and the disease.
Sepsis (continued). "This degradation is evident in sepsis models, where reduced GPX4 correlates with organ dysfunction and inflammation." (PMID 41250137, 2025). "A clinical study using patient serum samples reveals reduced GPX4 expression correlating inversely with proinflammatory markers such as IL-6 and TNF-α, with GPX4 levels predicting sepsis severity in pediatric cohorts (SOFA score > 10)." (PMID 41250137, 2025). "This study also highlighted an imbalance in the immune system during sepsis, potentially due to altered GPX4 function." (PMID 40364014, 2025). "WB revealed a significant upregulation of SLC7A11 and GPX4 expression, suggesting that rNrg4 mitigated the ferroptosis observed in sepsis-induced liver injury." (PMID 39956880, 2025). "Previous studies have validated that targeting the Nrf2/GPX4 axis effectively mitigates renal dysfunction in sepsis, a finding that supports our conclusion." (PMID 41020894, 2025). "Concurrently, MC-LR induces ferroptosis through the Nrf2/GPX4 pathway by decreasing GPX4 activity and accumulating iron ions, which further exacerbates the damage process and potentially leads to the onset of sepsis." (PMID 40723819, 2025). "It has been reported that GPX4 decreases lipid peroxidation and negatively regulates both ferroptosis and pyroptosis in lethal polymicrobial sepsis." (PMID 39822760, 2025). "Significantly, the conditional depletion of Gpx4 in bone marrow cells hastens systemic inflammatory responses and multi-organ failure in a mouse (Mus musculus) model of polymicrobial sepsis induced by cecum ligation and puncture." (PMID 40699725, 2025). "Decreased GPX4 leads to accumulation of lipid peroxidation products that damage cellular membranes and accelerate sepsis progression." (PMID 41008940, 2025). "Our results showed that GPX4 protein expression in the Cur + Sep group was significantly higher than that in the sepsis group, while renal Fe2+ and MDA levels were significantly lower." (PMID 41140036, 2025). "Collectively, these findings indicate that ACSL4, GPX4, and PTGS2, along with IL-6, hold significant diagnostic and prognostic value in sepsis." (PMID 40264754, 2025). "Enhancing GSH, via direct supplementation or activation of SLC7A11 and GPX4, also suppressed ferroptosis and myocardial injury in sepsis models." (PMID 41293242, 2025). "Extracellular vesicles also play protective roles: for example, ADSC-derived exosomal miR-125b-5p mitigates inflammation-induced pulmonary microvascular endothelial ferroptosis in sepsis-induced ARDS by regulating Keap1/Nrf2/GPX4 expression." (PMID 41383584, 2025). "PRDM16 plays a role in inhibiting ferroptosis through the NRF2/GPX4 axis or GPX4, thereby helping to prevent multi-organ injury induced by sepsis, which includes acute kidney injury (AKI)." (PMID 40867920, 2025). "In a CLP-induced sepsis model, a significant increase in ferroptosis was observed in the brain, characterized by downregulated GPX4, upregulated transferrin, and increased lipid peroxide levels." (PMID 41250137, 2025). "Shimizu and colleagues demonstrated that C23 treatment inhibits the downregulation of GPX4 expression and upregulation of ROS in the mice lungs during sepsis." (PMID 39794717, 2025). "A 2025 study demonstrated that iNOS knockout preserved GPX4 function and reduced ferroptosis in sepsis-induced ALI/ARDS." (PMID 41383584, 2025). "Third, while the role of the PRDM16/NRF2/GPX4 axis in sepsis-related injury has been well studied, more research is needed to understand its role in COPD, asthma, and PAH." (PMID 41199815, 2025). "In sepsis models, glutathione peroxidase 4 (GPX4) exerts a pivotal role in inhibiting ferroptosis, thereby mitigating sepsis-induced multi-organ damage." (PMID 40264754, 2025). "In sepsis-induced lung injury, ADSCs exosomes demonstrated a protective effect by inhibiting ferroptosis and up-regulating GPX4 expression in pulmonary microvascular endothelial cells." (PMID 39795932, 2024).
Sepsis (continued). "In summary, PRDM16 overexpression mitigates sepsis-induced multi-organ injury via upregulation of the NRF2/GPX4 axis." (PMID 39549609, 2024). "In lab tests, some studies have suggested that acetaminophen eases sepsis-induced cognitive impairment by reducing iron-induced cell death via the GPX4 and FSP1 signal pathways." (PMID 38357644, 2024). "Collectively, these findings suggest that PT-PRDM16-KO promotes ferroptosis, thereby worsening sepsis-induced AKI via the NRF2/GPX4 axis." (PMID 39549609, 2024). "The result is a reduction in the relative expression of signal transducer and activator of transcription 3 (STAT3) and glutathione peroxidase 4 mRNA with effects to be evaluated in the clinical setting in the management of patients with sepsis." (PMID 39768830, 2024). "Accumulated ROS leads to increased PL-PUFA-OOH level and inhibited GPX4 activity, which results in ferroptosis, thus exacerbating the development of sepsis." (PMID 38601213, 2024). "Irisin has also been shown to reduce ferroptosis in LPS-treated hepatocytes and CLP-induced sepsis models by modulating GPX4 expression." (PMID 39737174, 2024). "They activate TLR9/MyD88/NF-kβ pathway, up-regulate METTL3 expression, and promote m6A modification of GPX4, resulting in reduced GPX4 expression and triggering alveolar epithelial cell ferroptosis in the pathogenesis of sepsis-induced acute lung injury." (PMID 38988324, 2024). "In our research, it was demonstrated for the first time that PLGA-encapsulated formononetin upregulates PRDM16, which activates the NRF2/GPX4 pathway, thereby inhibiting ferroptosis and reducing sepsis-induced multi-organ injury, including AKI." (PMID 39549609, 2024). "In summary, PRDM16 inhibits ferroptosis via the NRF2/GPX4 axis or GPX4 to prevent sepsis-induced multi-organ injury, including AKI." (PMID 39549609, 2024). "In bacterial infection-mediated sepsis, GPX4 negatively regulates sepsis severity in macrophages and lethality in mice." (PMID 38844964, 2024). "Mucin 1 reduces Fe2+ and MDA, increases GSH and GPX4 expression, and improves sepsis-induced ALI through the Keap 1-NRF2-GPX4 pathway." (PMID 39670103, 2024). "Many studies have reported that NVP-AUY922 can alleviate Radiation-induced lung injury by inhibiting chaperone-mediated lysosomal degradation of GPX4, and has anti-inflammatory and antioxidant effects on preventing sepsis-induced MODS." (PMID 38641608, 2024). "The findings demonstrate that GPX4 is a crucial biomarker and a new latent immunotherapy target for the prediction and therapy of pediatric sepsis." (PMID 37443372, 2023). "In LPS‐induced in vitro sepsis model, subsequent to extracellular histone H3 treatment, LPS‐induced ferroptosis of HUVECs was enhanced, as evidenced by a decline in Gpx4 and an increase in ACSL4." (PMID 36705411, 2023). "Recent studies have suggested that dexmedetomidine alleviates sepsis-induced myocardial cellular injury by attenuating sepsis-induced HO-1 overexpression and increased iron concentration and reducing ferroptosis via enhancing GPX4." (PMID 37780755, 2023). "Level of ROS, Fe ion, and MDA was increased, and level of GSH and GPX4 was decreased, which means ferroptosis was induced by sepsis." (PMID 35038133, 2022). "Both GPX4 mRNA and protein levels were reduced in mice with sepsis compared with those in the control and sham groups." (PMID 35637949, 2022). "Although any single marker is sufficient to determine ferroptosis, here we adopted several downstream surrogate markers of the GPX4 pathway, i.e., lipid ROS and cell death, to rigorously establish that eCIRP serves as an inducer of ferroptosis in sepsis." (PMID 35844517, 2022). "Then, our team researched in depth the level of ferroptosis biomarkers such as cyclooxygenase-2 (COX-2) and glutathione peroxidase 4 (GPX4) in mice with sepsis-induced cardiomyopathy." (PMID 35397620, 2022). "In the present study, the levels of GPX4 were significantly decreased in sepsis-induced ferroptosis rats." (PMID 35038133, 2022).
Sepsis (continued). "The conditional knock-out of Gpx4 in myeloid cells results in an acceleration of the lethality of CLP sepsis, proving the pivotal and detrimental role of lipid peroxidation in CLP mice." (PMID 35052630, 2022). "In a model of cecum ligation puncture (CLP) sepsis, ferroptosis is progressively observed in the brain with glutathione peroxidase 4 (GPX4) inactivation and upregulation of transferrin." (PMID 35990689, 2022). "The data showed that the iron content and the expression of the pro-ferroptotic protein ACSL4 increased, while the anti-ferroptotic protein GPX4 expression reduced during sepsis." (PMID 35370723, 2022). "Mitochondria were the center of oxidative metabolism and played an important role in ferroptosis, while lipid peroxidation and GPX4 were critical targets for treating sepsis." (PMID 32997405, 2020). "In order to evaluate ferroptosis in sepsis, glutathione peroxidase 4 (GPX4), which was essential to maintain lipid homeostasis in the cells and negatively associated with the levels of ferroptosis, was used to detect ferroptosis in septic mice." (PMID 32997405, 2020). "GPX4 has been confirmed to possess dual regulatory functions: its deficiency not only exacerbates LPO but also promotes GSDMD‐dependent pyroptosis through caspase‐11 activation, significantly increasing mortality in sepsis models." (PMID 40919133, 2025). "Moreover, Ferrostatin-1, the inhibitor of ferroptosis, was found to rescue the downregulation of ferroptosis markers including cysteine/glutamate transporter (SLC7A11) and GPX4 in sepsis induced ALI/ARDS." (PMID 41383584, 2025). "Interestingly, they found that the α2-adrenergic receptor agonist dexmedetomidine reversed these changes, reducing ferroptosis by increasing GPX4 expression and decreasing iron concentration, thereby alleviating sepsis-induced cardiomyocyte damage." (PMID 40000618, 2025). "Specifically, RP105 helps protect renal cells from sepsis-induced ferroptosis by maintaining the expression of GPX4 and xCT, while suppressing the abnormal upregulation of HO-1, thereby reducing intracellular iron accumulation, lipid peroxidation, and oxidative stress." (PMID 40595455, 2025). "In our study, RP105 appeared to protect renal cells from sepsis-induced oxidative stress and ferroptosis by maintaining GPX4 and xCT expression levels and suppressing aberrant HO-1 activation, thereby reducing intracellular iron accumulation, lipid peroxidation, and oxidative stress." (PMID 40595455, 2025). "Similarly, the expression of Gpx4 in the liver in the Tac1+/+ mice with CLP-surgery-induced sepsis was lower than in the sham-operated controls (p < 0.001)." (PMID 38539834, 2024). "Since Gpx4 plays an important role in resisting lipid peroxidation, we verified the reduced Gpx4 expression by Western blotting and RT–PCR in HK-2 cells and LPS-induced sepsis-AKI model mice, respectively." (PMID 38149613, 2024). "A study showed that EVs from adipose-derived stem cells specifically deliver miR-125b-5p to alleviate inflammation-induced pulmonary microvascular endothelial cell ferroptosis in sepsis-induced ALI by modulating Keap1/Nrf2/GPX4 expression, thereby improving acute lung injury." (PMID 39809198, 2024). "We extracted the nucleus protein after melittin stimulation and found that the level of NRF2 was significantly elevated, implying that melittin may be dependent upon the upregulation of NRF2 for promoting GPX4 expression in sepsis-AKI." (PMID 38149613, 2024). "Furthermore, mitochondrial dysfunction in sepsis impairs antioxidant defenses, notably by reducing GPX4 activity." (PMID 39737174, 2024). "Thus, GPX4 knock-out can exacerbate the development of sepsis by possibly activating both cell death pathways." (PMID 38576612, 2024). "Therefore, targeting GPX4 represents a promising therapeutic approach for mitigating sepsis-induced renal damage." (PMID 39544947, 2024).
Sepsis (continued). "Recently, it has been reported that ferroptosis regulated by Glutathione Peroxidase 4 (GPX4) may be a new pathophysiological mechanism of sepsis, that inhibits ferroptosis from playing a protective role in septic lung injury." (PMID 38780016, 2024). "The usefulness of GPX4 as a marker in sepsis was assessed in a mouse model of sepsis." (PMID 37443372, 2023). "Furthermore, miR-125b-5p present in EVs from ADSCs can alleviate inflammation-induced ferroptosis in pulmonary microvascular endothelial cells (PMVECs) during sepsis-induced ALI by regulating the expression of Keap1/Nrf2/GPX4." (PMID 38343439, 2023). "In the sepsis-associated acute lung injury model, neutrophil extracellular traps induced ferroptosis in alveolar epithelial cells via activating the METTL3-YTHDF2-mediated m6A modification of GPX4." (PMID 38065948, 2023). "The results of our study show that ferroptosis was exacerbated in animal and cellular models of sepsis, as demonstrated by the decrease in the protein expression of Gpx4, increase in the protein expression of TF and FTH-1, and increase in serum Fe2+ levels compared with the sham groups." (PMID 37375325, 2023). "MFG-E8 reduced ferroptosis by activating GPX4, which might be an alternative treatment target for sepsis." (PMID 36463380, 2022). "More recently, the loss of glutathione peroxidase 4 (GPX4), which acts to prevent free radical generation and lipid peroxidation, was shown to promote caspase-11 and GSDMD-driven pyroptosis in a murine sepsis model." (PMID 35608339, 2022). "GPX4 plays a protective role in bacterial infection and multibacterial sepsis, and as an essential channel for iron death and coke death, GPX4 may be an important molecular target for the development of effective drugs for infection and sepsis." (PMID 34422728, 2021). "GPX4 was found to negatively regulate Gasdermin D-mediated pyroptosis in lethal polymicrobial sepsis by reducing lipid peroxidation; in contrast, conditional GPX4 knockdown in myeloid cells triggers macrophage pyroptosis with caspase-1/caspase-11-GSDMD-phospholipase C gamma 1 axis." (PMID 34899864, 2021). "Recently, it was reported that ferroptosis modulated by GPX4 might be a novel pathophysiological mechanism of sepsis." (PMID 32997405, 2020). "The antioxidant defense enzyme glutathione peroxidase 4 (GPX4) is a negative regulator of the pyroptotic cell death pathway, and plays an important role in inhibiting lethal inflammation associated with sepsis, which suggests that lipid peroxidation can drive GSDMD-mediated pyroptosis." (PMID 32182796, 2020). "Additionally, iNOS-derived nitric oxide in sepsis S-nitrosylates GPX4, inhibiting its activity." (PMID 41383584, 2025). "Sepsis-induced oxidative stress and GSH depletion impair GPX4 activity, triggering tubular cell death and renal dysfunction, while administration of ferroptosis inhibitors demonstrates protection against tubular necrosis and preservation of renal function in murine sepsis models." (PMID 41250137, 2025). "Additionally, the expression level of GPX4 in the Cur + Sep group was 44.2% ± 5.3%, significantly lower than that in the Sham group (78.2% ± 6.3%) and significantly greater compared to that in the Sepsis group (24.6% ± 4.5%) (p < 0.05)." (PMID 41140036, 2025). "Furthermore, GPX4 has been shown to confer protective effects against sepsis in mice." (PMID 40699725, 2025). "In sepsis‐associated ALI, neutrophil extracellular trap production activates the ferroptosis signal, and the expression of METTL3 increases significantly to induce m6A modification of glutathione peroxidase 4, thereby causing ferroptosis in AECs and worsening lung injury." (PMID 38757482, 2024). "Thus, GPX4 might negatively regulate pyroptosis by inhibiting lipid peroxidation, which prevents lethal polymicrobial sepsis in mice." (PMID 36898986, 2023).
Sepsis (continued). "Using both in vitro and in vivo studies, our findings show enhanced NETs accumulation in sepsis-associated ALI patients and mice, as well as the closely related upregulation of ferroptosis, the induction of which depends on METTL3-induced m6A modification of GPX4." (PMID 35637949, 2022). "The lower NETs level when PAD4 KO was accompanied by reduced ferroptosis in sepsis-associated ARDS mice, as demonstrated by reduced serum levels of ROS, ferritin and labile iron, reduced MDA and increased GSH levels in lung tissues, and increased GPX4 expression detected by qPCR and IHC staining." (PMID 35637949, 2022). "In addition, glutathione peroxidase-4 was found to play a protective role by modulating both ferroptosis and pyroptosis in bacterial infections and polymicrobial sepsis, suggesting that they may be potential therapeutic targets for treating sepsis." (PMID 35967871, 2022). "HMB protects lungs in experimental sepsis by inhibiting NF-κB inflammation, reducing ER and mitochondrial apoptosis, and boosting antioxidant defenses via NRF2/GPX4." (PMID 41711841, 2026). "Elevated SLC39A8 expression enhances lipid peroxidation while downregulating GPX4, FTH1, indicating that SLC39A8-driven ferroptosis plays a crucial role in the depletion of monocytes during sepsis." (PMID 40959429, 2025). "The first is the issue of biomarker recognition, which currently lacks validated sepsis-induced ALI/ARDS-specific ferroptosis biomarkers, and GPX4 activity in plasma acylcarnitine and BAL fluid cells is a promising candidate." (PMID 41383584, 2025). "Similar results were seen in LPS-induced sepsis, where liver MDA levels were elevated, and GSH, SLC7A11, and GPX4 expression was diminished in BAT-excised mice." (PMID 39956880, 2025). "Concurrently, sepsis depletes glutathione (GSH) by downregulating the xCT transporter, impairing GPX4 activity." (PMID 40893878, 2025). "However, whether GPX4 downregulation in sepsis involves abnormal ubiquitination remains unknown." (PMID 40156957, 2025). "Selenium (Se), a cofactor of GPX4, restores its activity; supplementation at 0.5 mg/kg increased GPX4 activity by 70% and reduced LPO in sepsis-induced ALI/ARDS mice." (PMID 41383584, 2025). "Through establishing in vivo cellular systems and ex vivo sepsis models, we deciphered the effects of hepcidin on SAKI and delineated its Nrf2/GPX4 signaling pathways in this study." (PMID 41020894, 2025). "This adjustment allowed for a more precise interpretation of the observed changes in CSN6 and GPX4 expression, reinforcing the conclusion that CSN6 contributes to ferroptosis in macrophages under sepsis conditions." (PMID 40595050, 2025). "Existing studies have shown that GPX4 is a negative regulator of ferroptosis, and activation of PDHA1 can ameliorate sepsis-induced acute kidney injury." (PMID 41445732, 2025). "In this study, we detected the serum levels of ACSL4, GPX4, and PTGS2 in ICU sepsis patients, non-sepsis patients, and healthy individuals." (PMID 40264754, 2025). "Consistent findings were observed in LPS-induced sepsis, where CL316243-treated mice showed reduced liver MDA levels and increased GSH, SLC7A11, and GPX4 expression." (PMID 39956880, 2025). "It plays significant roles in sepsis pathogenesis, with key molecular markers including PTGS2/COX2, SLC7A11 and GPX4." (PMID 40822455, 2025). "The results demonstrated a marked decrease in the expression of GPX4 and SLC7A11, while PTGS2 expression was significantly increased in liver tissues of the septic mice, suggesting that sepsis induces ferroptosis in liver tissues." (PMID 39512683, 2024). "This study showed a significant decrease in the expression of Gpx4 in the liver and lungs in mice following CLP-induced sepsis, which agrees with previous research." (PMID 38539834, 2024).